POU4F2 (POU class 4 homeobox 2)
Description:
Tissue-specific DNA-binding transcription factor involved in the development and differentiation of target cells. Functions either as activator or repressor modulating the rate of target gene transcription through RNA polymerase II enzyme in a promoter-dependent manner. Binds to the consensus octamer motif 5'-AT[A/T]A[T/A]T[A/T]A-3' of promoter of target genes. Plays a fundamental role in the gene regulatory network essential for retinal ganglion cell (RGC) differentiation. Binds to an octamer site to form a ternary complex with ISL1; cooperates positively with ISL1 and ISL2 to potentiate transcriptional activation of RGC target genes being involved in RGC fate commitment in the developing retina and RGC axon formation and pathfinding. Inhibits DLX1 and DLX2 transcriptional activities preventing DLX1- and DLX2-mediated ability to promote amacrine cell fate specification. Acts as a transcriptional coactivator via its interaction with the transcription factor ESR1 by enhancing its effect on estrogen response element (ERE)-containing promoter. Antagonizes the transcriptional stimulatory activity of POU4F1 by preventing its binding to an octamer motif. Involved in TNFSF11-mediated terminal osteoclast differentiation (By similarity).
Synonyms: Brn-3B; BRN3B; BRN3.2
Tractability: No criterion of Open Targets' tractability assessment is met for any kind of drug.
Gene: Protein-coding gene on chromosome 4 (146,638,893 to 146,642,474, forward strand). Ensembl gene ENSG00000151615.
Subcellular location: Nucleus; Nucleus speckle; Cytoplasm
Gene Ontology:
Molecular function: DNA-binding transcription activator activity, RNA polymerase II-specific; DNA-binding transcription factor activity, RNA polymerase II-specific; protein binding; RNA polymerase II cis-regulatory region sequence-specific DNA binding; DNA-binding transcription repressor activity, RNA polymerase II-specific; promoter-specific chromatin binding; chromatin binding; DNA binding; DNA-binding transcription factor activity; RNA polymerase II transcription regulatory region sequence-specific DNA binding; sequence-specific DNA binding
Biological process: estrogen receptor signaling pathway; MAPK cascade; positive regulation of transcription by RNA polymerase II; axon guidance; cellular response to cytokine stimulus; cellular response to estradiol stimulus; dorsal root ganglion development; heart development; negative regulation of amacrine cell differentiation; negative regulation of cell differentiation; negative regulation of transcription by RNA polymerase II; neuron differentiation; positive regulation of axon extension; positive regulation of cell differentiation; positive regulation of osteoclast differentiation; positive regulation of programmed cell death; positive regulation of transcription regulatory region DNA binding; regulation of retinal ganglion cell axon guidance; regulation of transcription by RNA polymerase II; retina development in camera-type eye; cellular response to insulin stimulus; cellular response to oxygen levels; negative regulation of adipose tissue development; positive regulation of cardiac muscle cell apoptotic process; and 4 more
Cellular component: nuclear speck; nucleus; transcription regulator complex; chromatin; cytoplasm; nucleoplasm; RNA polymerase II transcription regulator complex; euchromatin
Genetic constraint (gnomAD): Loss-of-function variants: 10 observed, 19.11 expected, observed/expected ratio (o/e) 0.52, 90% interval 0.32 to 0.89. The synonymous counts are far from expectation, so gnomAD's model fits this gene poorly and the ratio says little. Missense variants: 623 observed, 572.29 expected, observed/expected ratio (o/e) 1.09, 90% interval 1.02 to 1.16. Synonymous variants: 324 observed, 261.33 expected, observed/expected ratio (o/e) 1.24, 90% interval 1.13 to 1.36.
Homologues: Orthologues: chimpanzee POU4F2 (99% identical), rat Pou4f2 (99% identical), macaque POU4F2 (99% identical), mouse Pou4f2 (99% identical), dog POU4F2 (98% identical), guinea pig POU4F2 (98% identical), pig POU4F2 (97% identical), zebrafish pou4f2 (83% identical), rabbit POU4F2 (83% identical), tropical clawed frog pou4f2 (82% identical), Drosophila melanogaster acj6 (48% identical), Caenorhabditis elegans unc-86 (37% identical), and 2 more. Paralogues in human: POU4F1 (62% identical), POU4F3 (61% identical), POU3F3 (28% identical), POU3F2 (26% identical), POU2F1 (25% identical), POU3F4 (24% identical), POU2F2 (24% identical), POU3F1 (24% identical), POU2F3 (24% identical), POU6F2 (23% identical), POU1F1 (23% identical), POU5F1 (21% identical), and 5 more.
Diseases named in the same sentence as POU4F2 in open-access papers:
POU4F2 is named in the same sentence as 47 diseases in open-access papers, as found by Europe PMC text mining. Sharing a sentence is not in itself a finding about the gene and the disease. The quoted sentences say what the papers report.
breast carcinoma (8 papers, 2011 to 2021). "In breast cancer, POU4F2 can repress BRCA1 expression and interact with estrogen receptor alpha to enhance its activity." (PMID 27923066, 2016). "POU4F2 is overexpressed in breast cancer and neuroblastoma cells, in which it promotes tumor growth." (PMID 27923066, 2016). "For example, in MCF-7 breast cancer cells exposed to doxorubicin, survival cells are those that overexpress HspB1 consequently of the increased activity of the POU4F2/Brn-3b transcription factor." (PMID 24514166, 2014). "In human breast cancer cell lines, melatonin increased DNA methylation and induced downregulation of the oncogenes EGR3 and POU4F2/Brn-3b and upregulation of the tumor suppressor gene GPC3." (PMID 30386235, 2018).
bladder cancer (7 papers, 2012 to 2025). "Methylation levels of EOMES, HOXA9, POU4F2, TWIST1, VIM, and ZNF154 in urine specimens are promising diagnostic biomarkers for bladder cancer recurrence surveillance." (PMID 23056278, 2012). "In order to determinate whether POU4F2, C1, C2 and C3 can be utilized to diagnose bladder cancer in early-stage, we listed their sensitivities in different sub-categories of bladder cancer patients." (PMID 26700620, 2016). "The methylation status of a 4-gene panel (HOXA9, EOMES, POU4F2, and ZNF154) was significantly different between urine samples from bladder cancer patients and healthy individuals." (PMID 37627900, 2023). "In another study, the correlation between the methylation levels of EOMES, HOXA9, POU4F2, TWIST1, VIM, and ZNF154 in urine specimens and bladder cancer recurrence surveillance was discovered by real-time PCR." (PMID 33388091, 2021). "To analyze samples negative for BCL2 methylation, we expanded the MethyLight-based analysis by six additional promoter CpG islands previously reported to be frequently hypermethylated in bladder cancer, including CCNA1, EOMES, HOXA9, POU4F2, SALL3 and VIM2." (PMID 24732047, 2014). "Reinert and collaborators established a detailed mapping of the methylome in bladder cancer and identified four novel DNA methylation marks: HOXA9, ZNF154, POU4F2, and EOMES." (PMID 22829811, 2012). "In this study we performed an independent validation of EOMES, HOXA9, POU4F2, TWIST1, VIM, and ZNF154 methylation for the urinary diagnosis in bladder cancer surveillance." (PMID 23056278, 2012). "In addition, a 6-gene panel (HOXA9, EOMES, POU4F2, TWIST1, VIM, and ZNF154) was highly hypermethylated in the urine of bladder cancer patients as compared to healthy individuals." (PMID 37627900, 2023).
neuroblastoma (4 papers, 2011 to 2023). Neuroblastoma (NB) is the most common solid, extracranial childhood tumor. "The genes exhibiting methylation values above normal samples include the oncogene PHOX2B, the neuroblastoma associated gene ALX3, the commonly methylated PCDHα gene cluster, POU4F2, REXO1L1, BAPX1, and the potassium-channel KCNJ8." (PMID 22174824, 2011).
cerebrovascular accident (2 papers, 2023). "Overall, the key significantly upregulated genes based on FC values were Cyp2a5, Tgm1, and Lcn2 (2.4, 4.57, and 4.26 folds, respectively), whereas downregulated genes were Prl, Hcrt, and Pou4f2 (−4.35, −3.3, and −6.1 folds, respectively), at pre-, post-stroke day 1 and day 3, respectively." (PMID 37175797, 2023).
urothelial carcinoma (2 papers, 2025). A malignant neoplasm derived from the transitional epithelium of the urinary tract (urinary bladder, ureter, urethra, or renal pelvis). "First, the applicability of the Vimentin/POU4F2 methylation panel to other urothelial carcinomas—such as ureteral, renal pelvic, and upper tract tumors—remains to be determined." (PMID 41029537, 2025). "In order to develop the methylation assay for detecting urothelial carcinoma, we conducted a screening of 14 CpG sites in 7 genes (HIST1H4F, SOX1-OT, Vim, Onecut2, Twist1, NRN1, POU4F2) based on the literature review." (PMID 40855090, 2025).
Azoospermia (1 paper, 2025). Absence of any measurable level of sperm,whereby spermatozoa cannot be observed even after centrifugation of the semen pellet. "In line with the infertility observed in Brn-3b knockout mice, scRNA-seq data from human testes also reveal significantly reduced populations of POU4F2 (Brn-3b)-expressing cells in infertile men diagnosed with azoospermia and Klinefelter syndrome." (PMID 41282076, 2025). "The observed infertility in Brn-3b knockout mice, coupled with single-cell RNA sequencing (scRNA-seq) data revealing significantly reduced populations of POU4F2 (Brn-3b)-expressing cells in infertile men with azoospermia and Klinefelter syndrome, highlights its importance in human spermatogenesis." (PMID 41282076, 2025).
colorectal cancer (1 paper, 2024). A primary or metastatic malignant neoplasm that affects the colon or rectum. "POU4F2, as a POU homeodomain transcription factor, promotes the metastatic phenotypes of colorectal cancer." (PMID 37994607, 2024).
Infertility (1 paper, 2025). "Furthermore, the identification of rare and potentially pathogenic POU4F2 (Brn-3b) missense variants in an infertile man with Non-Obstructive Azoospermia provides compelling human genetic evidence supporting its etiologic role." (PMID 41282076, 2025).
male infertility (1 paper, 2025). The inability of the male to effect fertilization of an ovum after a specified period of unprotected intercourse. "These combined lines of evidence underscore the urgent need for future investigations into the functional consequences of POU4F2 (Brn-3b) variants in the context of human male infertility." (PMID 41282076, 2025). "Ultimately, a deeper understanding of the genetic and molecular contributions of POU4F2 (Brn-3b) could pave the way for novel diagnostic, prognostic, or therapeutic strategies to address male infertility and improve reproductive outcomes for affected couples." (PMID 41282076, 2025). "Taking all this evidence together, it strongly suggests that POU4F2 may also play a crucial role in human male infertility." (PMID 41282076, 2025). "This analysis revealed a potential genetic cause of human male infertility in a patient with Non-Obstructive Azoospermia, who carries two rare missense variants in POU4F2 (Brn-3b)." (PMID 41282076, 2025).
papillary thyroid cancer (1 paper, 2018). "Kikuchi et al26 identified multiple genes (HIST1H3J, POU4F2, SHOX2, PHKG2, TLX3 and HOXA7) with frequent epigenetic hypermethylation in papillary thyroid cancer, which might function as potential biomarkers." (PMID 30039914, 2018).
tumor (10 papers, 2009 to 2025). "To find out whether the dramatic expression variation of POU4F2 could be explained by differences at the genomic sequence we screened the promoter and coding parts of the gene for mutations by DNA sequencing in eight NB tumours." (PMID 19686582, 2009). "A comprehensive analysis was conducted to evaluate potential biases and diagnostic efficacy in demographic and clinicopathological characteristics, including age, gender, and tumor stage, of the Vimentin/POU4F2 combined methylation panel in urine DNA." (PMID 41029537, 2025). "In a recent study, the POU4F2 transcript has actually, in contrary to our results, been found to be expressed at a higher level in primary tumours of higher stages, especially in stage 3 tumours correlating negatively with MNA." (PMID 19686582, 2009). "The transcript discriminating groups with the largest fold change in verification group 1 was POU4F2, showing an expression level of more than 1500 times lower (p = 0,011) in the unfavourable tumours compared to the favourable ones." (PMID 19686582, 2009). "Altogether, a differential expression of POU4F2 has been observed in several individual studies, which indicates an important function of this transcription factor during the process of NB tumour progression." (PMID 19686582, 2009). "Depletion of POU4F2 has been shown to make cells resistant to apoptosis, indicating a tumour suppressor function." (PMID 19686582, 2009). "In this study the differential expression of POU4F2 was dramatic, as high as 1500 times difference in the first studied group of tumours." (PMID 19686582, 2009). "Some of the hypermethylated genes in TET2-wt CMML have been directly or indirectly related to cell cycle arrest, tumor suppression or myeloid differentiation (ZIC1, WT1, WNK2, MRPL41, POU4F2)." (PMID 22328940, 2012). "However, the analyses of POU4F2 and CNTNAP2 showed no genetic alterations that could explain a lower expression in unfavourable NB tumours." (PMID 19686582, 2009).
cancer (8 papers, 2009 to 2022). A tumor composed of atypical neoplastic, often pleomorphic cells that invade other tissues. "Importantly, growth factors like the epidermal growth factor (EGF) can stimulate the activity of the POU4F2 promoter and subsequently its mRNA and protein expression, which in turn can affect POU4F2 target genes influencing growth and behavior of cancer cells." (PMID 27923066, 2016). "EVs exclusively contained PLEKHG2 (nucleotide-binding protein), GPR68 (a proton sensing G protein-coupled receptor 68), POU4F2, ADAMTS9, and Let-7 microRNA precursor, which are involved in cell development, signal transduction, and cancer metastasis." (PMID 35663013, 2022). "A similar fraction of cancer samples showed high methylation in each gene (2/20 for HIST1H3J, 8/20 for POU4F2, 4/20 for SHOX2, 5/20 for PHKG2, 6/20 for TLX3, and 4/20 for HOXA7)." (PMID 24367375, 2013).
urinary diseases (1 paper, 2025). "In this study, we aimed to develop a non-invasive liquid biopsy assay capable of distinguishing BC from other urinary diseases using a combined Vimentin/POU4F2 methylation panel." (PMID 41029537, 2025).
POU4F2 also shares sentences with these, for which no sentence is quoted: cardiovascular disease (2 papers); glaucoma (2); heart failure (2); hyperglycaemia (2); infection (2); Insulin resistance (2); metabolic disease (2); Obesity (2); optic neuropathies (2); type II diabetes (2); acute monocytic leukemia (1); Anxiety (1); Blindness (1); breast (1); breast tumour (1); cardiac hypertrophy (1); coronary heart disease (1); Hypertension (1); kidney cancer (1); Klinefelter syndrome (1); melanoma (1); myocardial infarction (1); optic atrophy (1); ovarian adenocarcinoma (1); ovarian carcinoma (1); pineal parenchymal tumors (1); prostate carcinoma (1); retinal degeneration (1); retinal tumors (1); schizophrenia (1).
A further 4 diseases each share a sentence with POU4F2 in 1 paper.